VDR (vitamin D receptor)
Diseases named in the same sentence as VDR in open-access papers (continued):
Sharing a sentence is not in itself a finding about the gene and the disease.
Stroke (10 papers, 2018 to 2025). Sudden impairment of blood flow to a part of the brain due to occlusion or rupture of an artery to the brain. "This further corroborates VDR as a key determinant in regulating the immune signatures of microglia/macrophages in stroke pathophysiology." (PMID 36890539, 2023). "Collectively, VDR signaling in microglia/macrophages plays a crucial role in restraining ischemia-elicited neuroinflammation and stroke progression." (PMID 36890539, 2023). "In summary, our study reveals a novel regulatory mechanism by which VDR signaling in microglia/macrophages modulates neuroinflammation and stroke pathogenesis following cerebral ischemia." (PMID 36890539, 2023). "Our results suggest that 1,25-D3 promotes angiogenesis by up-regulating TGF-β/Smad2/3 signaling pathway via VDR activation, thereby alleviating ischemia/reperfusion injury and improving stroke outcomes in rats." (PMID 35369317, 2022). "Regarding the patients’ background, there were still significant differences in atrial fibrillation, stroke, blood urea nitrogen, uric acid, ferritin, pH, bicarbonate, and the use of vitamin D receptor agonists." (PMID 33823813, 2021). "The effect of stroke was first assessed on the expression of VDR and metabolizing enzymes in the brain and spleen at 24 h in otherwise untreated animals." (PMID 29476479, 2018). "To determine whether VDR signaling in microglia/macrophages would have a specific impact on stroke progression and outcome, we generated inducible Vdr conditional knockout (Vdr-cKO: Cx3cr1CreER/+; Vdrf/f) mice by crossing Vdrf/f mice with Cx3cr1CreER mice." (PMID 36890539, 2023). "Indeed, we found that VDR ablation in microglia/macrophages markedly impaired BBB integrity after stroke, as evidenced by reduced expression of endothelial tight junction proteins, ZO-1 and Claudin-5, 3 days after MCAO." (PMID 36890539, 2023). "Whether VDR signaling could modulate stroke outcomes in a sex- and age-dependent manner warranted further investigation." (PMID 36890539, 2023). "Therefore, 1,25-D3 promotes angiogenesis after stroke by activating VDR, thus promotes the activation of TGF-β subtypes and the expression of VEGF mRNA." (PMID 35369317, 2022). "However, it has been shown that 1,25(OH)2D3/VDR interaction can protect against stroke-inflicted BBB disturbance via the inhibition of NF-κB activation and, therefore, downstream MMP-9 expression." (PMID 34393969, 2021). "Stroke increased expression of the VDR by ~twofold in both organs." (PMID 29476479, 2018). "We found that expression of the VDR was elevated in both organs after stroke." (PMID 29476479, 2018). "Results showed that the expression of VDR, TGF-β, p-Smad2/Smad2, p-Smad3/Smad3, and VEGF in the periinfarcted cortex was significantly higher than DMSO group 3 days after stroke." (PMID 35369317, 2022). "1,25-D3 activated VDR then up-regulated TGF-β/Smad2/3 signaling pathway and enhanced VEGF production, which contribute to promoting angiogenesis and improving stroke outcomes in rats after stroke." (PMID 35369317, 2022). "Therefore, via VDR activity, high levels of vitamin D are suggested to be directly neuroprotective via stabilization of the BBB post-stroke." (PMID 34393969, 2021). "Vitamin D-VDR signaling axis in microglia/macrophages is a crucial modulator of poststroke neuroinflammation and outcomes, whereas this finding did not preclude the importance of VDR in other brain cell types, such as astrocytes and neurons, during stroke pathogenesis." (PMID 36890539, 2023).
acute myeloid leukemia (9 papers, 2013 to 2022). Acute myeloid leukemia (AML) is a group of neoplasms arising from precursor cells committed to the myeloid cell-line differentiation. "For example, 1,25(OH)2D3 or VDR activation can significantly induce hCAP18 expression in acute myeloid leukemia cells." (PMID 35039485, 2022). "Methylation of VDR promoter was shown to be important in acute myeloid leukemia cells and DNA methyltransferase inhibitor 5-aza induced VDR expression." (PMID 36246903, 2022). "Use of VDR agonists with hypomethylating agents decreased tumor burden in acute myeloid leukemia mouse models." (PMID 36246903, 2022). "RARα takes part in regulation of VDR transcription, and unliganded RARα acts as a transcriptional repressor to VDR gene in acute myeloid leukemia (AML) cells." (PMID 28635660, 2017). "Nrf2 can mediate the 1α,25-dihydroxyvitamin D3-induced differentiation of acute myeloid leukemia cells through multiple mechanisms, including VDR/RXRα transcription." (PMID 23408904, 2013). "Moreover, VDR was identified as a new genetic modifier contributing to the expression of different subtypes or acute myeloid leukemia." (PMID 32397406, 2020). "In some human acute myeloid leukemia (AML) blasts, the expression of the VDR gene is also high." (PMID 32872475, 2020). "In this study, we show that in acute myeloid leukemia (AML) cells, high expression of vitamin D receptor gene (VDR) is needed for strong and sustained upregulation of CEBPB gene, while the moderate expression of VDR is sufficient for upregulation of CEBPD in response to 1,25D." (PMID 29966306, 2018).
autism (9 papers, 2014 to 2025). Persistent deficits in social interaction and communication and interaction as well as a markedly restricted repertoire of activity and interest as well as repetitive patterns of behavior. "Six of the autism patients have the heterozygous (CT) genotype in the VDR TaqI (rs731236) variant, and one has the homozygous (CC) genotype." (PMID 38807972, 2024). "Five of the autism patients carry the homozygous (CC) genotype in the VDR FokI (rs2228570-C) variant, and three carry the heterozygous (AC) genotype." (PMID 38807972, 2024). "Considering the VDR ApaI (rs797522-C) genetic variant, five of the autism patients have the heterozygous (AC) genotype, and two have the homozygous (AA) genotype." (PMID 38807972, 2024). "Considering the VDR ApaI (rs7975232) genetic variant, 5 of the autism patients have the heterozygous (AC) genotype, and 2 have the homozygous (AA) genotype." (PMID 38807972, 2024). "Six of the autism patients have the heterozygous (CT) genotype in the VDR TaqI (rs731236-C) variant, and one has the homozygous (CC) genotype." (PMID 38807972, 2024). "Six of the autism patients are heterozygous (AG), and one has a homozygous (AA) genotype in the VDR BsmI (rs1544410-A) polymorphism." (PMID 38807972, 2024). "In this study, we investigated the genetic association of four different VDR polymorphisms (Apa-I, Bsm-I, Taq-I, Fok-I) with susceptibility to the development of autism in children." (PMID 28891930, 2017). "When examining the associations between genetic variants and diseases, VDR FokI, VDR ApaI, and VDR BsmI variants were more frequently observed in patients with Hashimoto’s thyroiditis, while the VDR TaqI variant was more common in individuals with autism." (PMID 41340975, 2025). "Both autism patients are at risk of being heterozygous (AC) for the VDR FokI variant." (PMID 38807972, 2024). "One variant upstream of the gene disrupts or creates binding sites for transcription factors such as the vitamin D receptor and OTX, which have been implicated in psychiatric disorders including autism, thus potentially modulating ANXA1 expression." (PMID 24720851, 2014). "While one of the autism patients has no risk in the VDR ApaI variant, one has the homozygous (CC) genotype." (PMID 38807972, 2024). "The VDR, a member of the nuclear steroid receptor family, is expressed in several human brain structures and is therefore a suitable candidate gene for autism development." (PMID 28891930, 2017). "There is no risk of the VDR TaqI variant in autism patients." (PMID 38807972, 2024).
cognitive decline (9 papers, 2011 to 2025). "A second study by Gatto and colleagues assessed the role of VDR polymorphisms in cognitive decline in patients with PD." (PMID 32536905, 2020). "A meta-analysis showed that VDR BsmI and FokI polymorphisms were associated with the risk of PD, and VDR FokI genotype was associated with the severity and cognitive decline of PD." (PMID 30915197, 2019). "Associations between polymorphisms in the vitamin D receptor (VDR), age- dependent cognitive decline, and insufficient serum 25 hydroxyvitamin D3 levels in Alzheimer's patients and elderly people with cognitive decline have been reported." (PMID 21408608, 2011). "And study demonstrated that VDR polymorphisms were associated with cognitive decline in PD." (PMID 41346436, 2025). "The VDR protein that results from the A variant has less transcriptional activity compared to the G variant allele, suggesting that lower VDR activity contributes to cognitive decline." (PMID 32536905, 2020). "Some studies showed an association between vitamin D receptor (VDR) gene polymorphisms and cognitive decline, AD." (PMID 36569670, 2022). "Whether this gene expression pattern regulated by VDR could impact on poststroke long-term neurological sequelae, such as cognitive decline, awaits to be elaborated in future studies." (PMID 36890539, 2023). "Dysregulation of VDR signaling, whether through deficiency or genetic polymorphisms (e.g., FokI, BsmI), may impair dopamine synthesis and neuronal survival, contributing to both motor symptoms (bradykinesia, rigidity) and non-motor features (cognitive decline, mood disorders)." (PMID 41441206, 2025).
cutaneous melanoma (9 papers, 2014 to 2024). A primary melanoma arising from atypical melanocytes in the skin. "Previously we have observed a positive association between low VDR expression and increasing tumor stage in cutaneous melanomas (Breslow thickness, Clark level, pTNM stage, overall stage, and presence of negative prognostic markers) with lack of or low VDR expression determining poorer prognosis." (PMID 26501255, 2015). "In 2010, Brożyna and co-authors showed that as the malignancy of cancer increases, the expression of the VDR decreases in patients with skin melanoma." (PMID 34206371, 2021). "VDR expression was quantified immunohistochemically in 69 cutaneous melanomas and compared to the tumors’ pTNM (pathological tumor, node, metastasis) stage, ulceration, and tumor-infiltrating lymphocytes." (PMID 34692525, 2021). "We also demonstrate that knocking out VDR expression in human skin melanoma cells increases their proliferation and colony and spheroid formation capacity." (PMID 34206371, 2021). "Similar observations were made in the studies cutaneous melanoma, where the level of VDR decreased together with an increase of melanin content and poorer prognosis." (PMID 31235702, 2019). "Knocking out of VDR expression in the WM164 human skin melanoma cell line not only caused changes in cell morphology but also accelerated the growth rate, as measured by proliferation and colony formation assays." (PMID 34206371, 2021). "This suggests that expression of VDR is connected with the tumor malignancy of human skin melanoma." (PMID 34206371, 2021). "Similarly as in the cells of cutaneous melanoma, VDR immunostaining has been found in uveal melanoma both in cell nuclei (VDRn) and in cytoplasm (VDRc)." (PMID 31235702, 2019). "Also in skin melanoma, a significantly decrease in the expression of VDR, CYB27B1, CYP24A1, RORα and RORγ was observed in comparison to normal melanocytes or perilesional keratinocytes." (PMID 31235702, 2019). "Previously we showed a negative correlation of vitamin D receptor (VDR) and CYP27B1 expression with progression, aggressiveness and overall or disease-free survivals of skin melanomas." (PMID 25334067, 2014).
Hashimoto thyroiditis (9 papers, 2016 to 2025). An autoimmune disorder caused by the production of autoantibodies against thyroid tissue. "The bar charts revealed mild, group-specific variations, particularly in CYP2R1 and GC polymorphisms within the ASD group and in VDR variants within the Hashimoto’s thyroiditis group." (PMID 41340975, 2025). "Four VD receptor (VDR) gene polymorphisms (TaqI, ApaI, FokI and BsmI) have been reported to influence Hashimoto’s thyroiditis (HT) risk." (PMID 28134349, 2017). "In the Croatian population was described an association between VDR polymorphisms haplotypes and Hashimoto’s thyroiditis risk." (PMID 27011770, 2016). "However, subtle yet notable differences were observed, particularly in CYP2R1 and GC polymorphisms within the ASD group and in VDR variants within the Hashimoto’s thyroiditis group." (PMID 41340975, 2025). "Review objectives and a concise summary of the methodology: The review aims to analyze studies examining the relationship between specific VDR polymorphisms, vitamin D levels, and the development of various diseases, with a particular emphasis on Hashimoto’s thyroiditis." (PMID 41226614, 2025). "It has been emonstrated that inappropriate mRNA expression was observed in T lymphocytes from 45 patients with Hashimoto’s thyroiditis, resulting in reduced VDR transcription levels compared with 13 euthyroid controls." (PMID 41226614, 2025). "Furthermore, most studies focus on the association of VDR polymorphisms with susceptibility to developing Hashimoto’s thyroiditis, not directly on the severity of disease symptoms." (PMID 41226614, 2025).
hypothyroidism (9 papers, 2019 to 2025). Abnormally low levels of thyroid hormone. "Polymorphisms of the VDR are related to the predisposition of people to thyroid disorders such as hypothyroidism." (PMID 34425794, 2021). "The current study aimed at assessing vitamin D level and vitamin D receptor polymorphism in hypothyroid Egyptian patients and its effect on hypothyroidism and thyroid morphology, also to find a causal relation between vitamin D and hypothyroidism." (PMID 31534663, 2019).
hypovitaminosis (9 papers, 2015 to 2025). "If vitamin deficiency persists for a long time, the function of the vitamin D receptor (VDR) in the muscle will be altered, with the consequent formation of ROS and altered mitochondrial function." (PMID 35162272, 2022). "In support, VDR activation and hypovitaminosis D have been previously linked to forkhead box protein O1 activity." (PMID 33266123, 2020). "In this line, patients suffering from TB have shown either vitamin deficiency or vitamin D receptor (VDR) polymorphisms." (PMID 31824513, 2019). "Intestinal epithelial vitamin D receptor is important in the regulation of mucosal inflammation by maintaining the integrity of the mucosal barrier, suggesting hypovitaminosis D may also perpetuate inflammation." (PMID 26333093, 2015).
intervertebral disc degeneration (9 papers, 2012 to 2023). "PubMed, EMBASE, Cochrane library, Web of Science and China Knowledge Resource Integrated Database for papers on VDR gene polymorphisms and risk of intervertebral disc degeneration were searched." (PMID 34011063, 2021). "This study aimed to drive a more precise estimation of association between VDR gene polymorphisms and risk of intervertebral disc degeneration." (PMID 34011063, 2021). "Numerous studies have investigated the associations between Vitamin D receptor (VDR) gene polymorphisms and risk of intervertebral disc degeneration but the results remain controversial." (PMID 34011063, 2021). "The aim of this investigation, therefore, was to study the association of the aggrecan gene (ACAN) variable number tandem repeat (VNTR) and the vitamin D receptor (VDR) rs731236 (TaqI) polymorphisms, with lumbar intervertebral disc degeneration in a population in the North of Iran." (PMID 35919638, 2022). "Considering the intervertebral disc degeneration (IDD)-related pathologies, few in vitro studies reported the presence of human cells expressing the vitamin D receptor (VDR) inside the disc, which are able to respond to the hormone by modulating proliferative and metabolic pathways." (PMID 34502510, 2021).
left ventricular hypertrophy (9 papers, 2014 to 2024). Enlargement of the LEFT VENTRICLE of the heart. "Vitamin D receptor polymorphisms, such as B alleles of BsmI, with altered vitamin D signaling, are genetic risk factors for the development of left ventricular hypertrophy in kidney disease." (PMID 26000280, 2015). "In thissense, Testaet al.74 and El-Shehaby etal. observed that, in patients ondialysis, the B allele of the BsmI polymorphism in the vitamin D receptor gene wasindependently related to left ventricular hypertrophy and is associated with agreater rate of its progression." (PMID 29944163, 2018). "The VDR is activated by VDR activators, such as calcitriol, paricalcitol and alfacalcidol, to prevent cardiac fibrosis through inhibition of left ventricular hypertrophy." (PMID 32235811, 2020). "Vitamin D receptor knockout mice had upregulated matrix metalloproteinases, involved in cardiac remodeling, impaired cardiac relaxation and contractility, and developed left ventricular hypertrophy." (PMID 26000280, 2015).
liver cancer (9 papers, 2003 to 2025). An epithelial or non-epithelial malignant neoplasm that arises from the liver. "The SNPs in PNPLA3 and VDR genes, associated to the development of chronic liver disease and progression towards liver cancer, have been characterized in 258 healthy unrelated male volunteers." (PMID 26219465, 2015). "In liver cancer cells, VDR is present in human HCC lines and patient samples, potentially regulated by KLF4." (PMID 41041128, 2025). "SQSTM1 was reported to inhibit hepatic stellate cell activity, fibrosis, and liver cancer by binding to the vitamin D receptor." (PMID 36795724, 2023). "VDR is expressed in both human liver cancer cell lines, especially HepG2 cell lines and specimens of human HCC." (PMID 35505652, 2022). "In the context of liver cancer, higher VDR gene promoter methylation was detected in the HCC tissue." (PMID 35505652, 2022). "Recently, Duran and colleagues found that the vitamin D receptor inhibits liver cancer as well as fibrosis through a process involving p62/SQSTM1 ligation of the VDR." (PMID 29659559, 2018). "In human liver cancers, one study has found VDR mRNA expression in all 10 tumours tested, another study found VDR in 10 of 18 tumours tested with a radioreceptor assay." (PMID 12865912, 2003). "However, in certain circumstances, VDR expression may be reduced in liver cancer tissue, providing an escape mechanism from vitamin D effects." (PMID 35505652, 2022). "Besides environmental, behavioral, viral and metabolic factors, genetic polymorphisms in patatin-like phospholipase-3 (PNPLA3) and vitamin D receptor (VDR) genes have been related to the development of chronic liver disease and progression towards liver cancer." (PMID 26219465, 2015). "Multiple previous literatures have confirmed that the activation state of VDR can modulate the functions of non-parenchymal and parenchymal liver cells, such as fibrogenesis, integrity of biliary epithelial cells, liver cancer, and BA metabolism." (PMID 32296329, 2020).